ATM (ATM serine/threonine kinase)
Diseases named in the same sentence as ATM in open-access papers (continued):
Sharing a sentence is not in itself a finding about the gene and the disease.
cancer (continued). "Mutations in the human ATM gene can cause the cancer-prone disorder ataxia telangiectasia." (PMID 23592994, 2013). "We are interested in understanding how changes in miRNA expression due to ATM deficiency may contribute to cancer predisposition and elicit alterations in normal physiological pathways." (PMID 23741392, 2013). "This initial observation suggests a means by which the loss of ATM might predispose cells to cancer or increase cancer-susceptibility." (PMID 23741392, 2013). "When we compared the miRNA expression between the wild type and ATM-deficient HME-CCs we discovered that the miRNAs dis-regulated after the depletion of ATM show an unusually high correlation with miRNAs implicated in cancer." (PMID 23741392, 2013). "Given the important roles of ATM in response to DNA damage, inherited variability in this gene could directly or indirectly contribute to susceptibility to cancer." (PMID 22276117, 2012). "Mutation of ATM in humans can lead to Ataxia-telangiectasia (A-T), a rare autosomal recessive disorder, one of the hallmarks of which is a predisposition to developing cancer." (PMID 22350747, 2012). "Hence, understanding the molecular mechanisms underlying the regulation of ATM in cancers has received much attention." (PMID 21980462, 2011). "Constantly, ATM deficient mice displayed growth retardation, neurologic dysfunction, radiosensitivity, sterility, defects in T lymphocyte maturation and predisposition to cancers with increased levels of hematopoietic malignancies in particular." (PMID 21980462, 2011). "ATM (ataxia telangiectasia mutated) is a key protein responsible for arresting the cell cycle in response to DNA damage and has a role in genetic stability and cancer susceptibility." (PMID 21496344, 2011). "Somatic mutations of ATM have been also associated with human cancers." (PMID 21054854, 2010). "Interestingly, PARK2 and ATM mutations in cancer sometimes occur at the exact same residue, causing neuronal degeneration." (PMID 21203498, 2010). "Additional experiments are under way to confirm this synthetic lethal effect and to test whether these compounds are effective in human ATM-deficient cancer cells as well." (PMID 20043851, 2009). "ATM deficiency in humans results in a rare, multi-system disorder, ataxia–telangiectasia (A–T), characterized by cerebellar degeneration with ataxia, telangiectasia, chromosomal instability, radiosensitivity and cancer predisposition." (PMID 19008195, 2009). "It would be expected, therefore, that genetic changes in terms of mutations in any of the individual components of ATM-associated pathways may constitute a significant risk factor in current or former smokers in terms of cancer development." (PMID 17594478, 2007). "Mutations in the ATM gene cause ataxia-telangiectasia (A-T), a rare recessive disorder characterized by progressive neurodegeneration, cell cycle checkpoint defects, radiosensitivity and increased risk of cancer, particularly of lymphoid malignancies." (PMID 16914028, 2006). "Consequently, our findings may have broader implications for other HR-proficient cancers exhibiting concurrent cyclin D1 overexpression and ATM deficiency and suggest a biomarker-driven approach for the development of inhibitors of POLΘ." (PMID 40608419, 2025).
cancer (continued). "Moreover, ATM inhibition in normal cells has been associated with severe adverse effects, as well as homozygous individuals exhibiting a predisposition to early-onset cancers and severe adverse reactions to conventional RT doses." (PMID 40978282, 2025). "When considering the implications of ATM status, this should be viewed as part of the complex relationship between DNA repair and cancer: the loss of genome stability is an important characteristic driving many cancers, but it also makes cancer cells potentially susceptible to genotoxic therapies." (PMID 40723241, 2025). "Moreover, the survival of BRCA1- or ATM-deficient cancer patients could be triaged by SETD1A expression, which was not the case for those with deficiencies in BRCA2, nor those with functional copies/levels of these genes." (PMID 39994444, 2025). "Interestingly, he also had a prolonged response to irinotecan, which may further suggest that the ATM mutation originated from his cancer." (PMID 40622001, 2025). "While some DRP variants may be germline, their contribution to genomic instability, exemplified by the ATM cancer variant in the highest mutational burden sample (TC627), could explain the heterogeneous mutational landscape and facilitate tumor progression in canine TC." (PMID 41353477, 2025). "However, across the literature multiple roles of ATM have been implicated in cancer." (PMID 38933336, 2024). "Consistently, cell assays in vitro showed that cancer cells with driver genetic alterations accompanied by ATM deficiency had high capability in proliferation and invasion, thus suggesting that ATM may assist driver oncogenes in enhancing tumor-promoting effects." (PMID 38886866, 2024). "For the patients with single primary cancer, among 542 evaluable patients (those with both germline and somatic mutations which were in same or different genes), 25 patients (4.6%) had biallelic events, and the involved genes included ATM, BRCA1, BRCA2, BRIP1, and ERCC5." (PMID 37885353, 2024). "Finally, considering that ATM is frequently mutated, deleted, or methylated in various cancers, a defect in amino acid (cysteine/glutamate) metabolism may also offer new therapeutic targets that could be explored in those contexts." (PMID 39281865, 2024). "Nevertheless, our finding of relatively frequent somatic ATM alterations across many of the atypical cancer types has been corroborated by an analysis showing that ATM was among the most frequently mutated genes in the DNA-damage response pathway across 33 distinct types of cancers." (PMID 36865800, 2023). "Furthermore, the study suggests that the model is well-calibrated for moderate penetrance genes such as CHEK2 and ATM, which may have implications for the validity of cancer risk predictions." (PMID 37237042, 2023). "However, it is unclear how ATM is associated with tumorigenesis and cancer aggressiveness." (PMID 37020276, 2023). "An important aspect of ATM activity is the ATM cytoplasmic-nuclear shuttling process that allows radiosensitivity (seen in IR tissue reactions) to be distinguished, radiation-susceptibility for the induction of cancer, and IR-induced degeneration and senescence." (PMID 37511215, 2023). "Homozygous or compound heterozygous germline ATM mutation causes ataxia-telangiectasia, an autosomal recessive multisystem disorder presenting in childhood with progressive cerebellar ataxia, oculocutaneous telangiectasia, immune deficiency, radiosensitivity, and cancer predisposition." (PMID 35628590, 2022). "In addition, many of these ATM residues have been found mutated in cancer." (PMID 35076389, 2022). "Recent findings also suggest that there may be a common pathogenic mechanism that connects a high prevalence of cancer, metabolic disorders, atherosclerotic cardiovascular disease, and insulin-resistant diabetes in carriers of some DNA repair defects, in particular ATM mutations." (PMID 34484227, 2021).
cancer (continued). "Interestingly, all eight ATM PV carriers in our study had a positive family cancer history (this may explain a significant association with the PDAC risk in the Belgian subgroup only, enriched in such patients)." (PMID 34503238, 2021). "However, ATM loss was reported to sensitize several other cancer cells to PARPi." (PMID 34320214, 2021). "In addition, although ATM is considered a tumor suppressor, ATM mutations can enhance chemo-radioresistance to tumor cells, and this could be useful to explore as a potential target for cancer treatment." (PMID 34068084, 2021). "Furthermore, using multi-omics analyses, the authors of that study found an association between CTL infiltration in cancers with chromosomal instability and phosphorylation of the Ataxia Telangiectasia Mutated (ATM) protein, a DNA double-strand break damage response protein." (PMID 34440251, 2021). "Moreover, olaparib acts synergistically with ATRi (AZD6738) in ATM deficient cancer cells." (PMID 33352723, 2020). "Thus, it appeared necessary to consider therapeutic approaches that may enhance the efficacy of PARP inhibition in ATM-deficient cancers." (PMID 32183301, 2020). "Consequently, ATM-deficient cancers could be closer to mitotic catastrophe and thus more vulnerable to exogenous DNA damage." (PMID 32444694, 2020). "However, in cancer treatment, somatic ATM deficiency in cancer cells has a different manifestation." (PMID 32566127, 2020). "Accordingly, cell lines derived from A–T patients and ATM knock out mice are hypersensitive to IR and other chemotherapeutic agents, raising the possibility that cancers with loss of ATM may be more sensitive to DNA damaging agents than their ATM-proficient counterparts." (PMID 32183301, 2020). "Thus, the combination of PARP and ATR inhibitors could be beneficial in a number of ATM-deficient cancers, including lung, prostate and pancreatic." (PMID 32183301, 2020). "In addition to germline variants, somatic ATM alterations commonly occur in a number of sporadic human cancers, in particular leukemias and carcinomas of the breast and lung, and these findings generate new opportunities for the future treatment of these tumors." (PMID 32046255, 2020). "This might explain the increased cancer risk of ATM mutation carriers." (PMID 32015826, 2020). "This could well explain our findings that individuals with ATM rs189037 suffer more cancer risk." (PMID 31201228, 2019). "It has long been debated whether a monoallelic truncating ATM variant may increase cancer risks." (PMID 31882575, 2019). "Reduced ATM expression may impair its normal function, lead to uncontrolled cell cycle, abnormal DNA repair and apoptosis, and finally increase the susceptibility to cancer." (PMID 31201228, 2019). "For example, cancer cells can tolerate higher levels of replication stress that result from the overexpression of oncogenes because of the amplification of replication stress response kinases, such as ataxia telangiectasia mutated (ATM) and Rad3-related (ATR) kinase." (PMID 31640753, 2019). "Moreover, ATM mutations can lead to deficiencies in DNA repair, which in return may give rise to cancer." (PMID 28497333, 2017). "In addition, ATM-deficient cancer cells show strong addiction to DNA-PK." (PMID 29088817, 2017).
cancer (continued). "An additional hindrance in the assessment of the functional consequences of ATM mutations is the evaluation of zygosity, as cancer cells are frequently aneuploid and even deleterious mutations might not result in any phenotypic consequences if one or several wildtype (wt) alleles are present." (PMID 27602502, 2016). "While the majority of A-T patients (~90%) have truncating ATM mutations that result in little or no ATM protein expression, missense ATM mutations are more common in cancers and with the exception of the few that cause A-T, their biological functions are unknown." (PMID 27304073, 2016). "Functional loss of ATM, caused by hereditary mutations in the gene predisposes individuals to Ataxia Telangiectasia (A-T); an autosomal recessive disorder characterized by neurodegeneration, immune deficiency, hypersensitivity to ionizing radiation and increased frequency of cancers." (PMID 26275218, 2015). "Likewise, germline mutations in ATM result in the autosomal recessive disorder Ataxia-telangiectasia, a neurodegenerative disorder characterized by hypersensitivity to ionizing radiation and a 100-fold increased risk of developing cancer." (PMID 24792170, 2014). "Interestingly, they suggest that downregulation of ATM levels, which frequently occurs in cancer, may be linked to the escape of the repression of mTORC1 to allow tumor growth in hypoxia." (PMID 24681585, 2014). "Overall, these observations reveal the complex architecture that characterizes the activity of ATM in the DNA-damage response, the maintenance of genetic stability, and cell-cycle regulation, and how this multifunctional activity correlates with genetic predisposition or sporadic onset of cancer." (PMID 25247188, 2014). "Polymorphisms in ATM, which affect normal protein activity, may alter the efficiency of cell cycle checkpoint activation, DNA repair and induction of apoptosis and lead to genetic instability and increased cancer risk." (PMID 22276117, 2012). "Inhibiting the FA pathway in ATM deficient cells can be achieved with small molecule inhibitors, suggesting that new cancer therapeutics could be developed by identifying FA pathway inhibitors to treat cancers that contain defects that are synthetic lethal with FA." (PMID 22693661, 2012). "Interestingly, administration of antioxidant (e.g. EUK-189 and NAC) to ATM-deficient mice lowers oxidative DNA, lipid, and protein damages, reduces cancer incidences, inhibits cerebellar Purkinje cell death, and partially reverses the neurological deficits and premature aging seen in these mice." (PMID 18431490, 2008). "Simultaneously, developing radiosensitizers tailored to genetic vulnerabilities (e.g., PARP inhibitors for SMAD4- or BRCA-mutant tumors, ATR inhibitors for ATM-overexpressing cancers) will expand therapeutic options." (PMID 40725389, 2025). "DSB repair plays a vital role in acquired resistance to radiotherapy and chemotherapy in many cancers; therefore, it is essential to clarify the involvement of ATM in these processes." (PMID 40144209, 2025). "Of these, 103 patients (8.6% of the total sample) carried germline pathogenic variants in genes that have been definitively linked to an increased risk of PC or other types of cancers (BRCA2, ATM, CHEK2, NBN, BRCA1, PALB2, BRIP1 and BARD1)." (PMID 41465280, 2025). "This is particularly apparent in cancer, where cells hijack DDR by upregulation of the key DDR proteins Ataxia Telangiectasia and Rad3-related protein (ATR) and/or Ataxia Telangiectasia Mutated (ATM)." (PMID 40514450, 2025). "The molecular mechanisms of cancer pathway included variants in the following COSMIC driver genes: CASP8 (high impact; VAF = 0.036 in HCC tumor) and ATM (moderate impact; VAF = 0.029 in HCC cell line and VAF = 0.012 in HCC tumor)." (PMID 40340757, 2025). "The cancer-associated transcripts including NF1, ATM, MUC16, and KMT2C, were found at higher mRNA levels with ExCy." (PMID 40598203, 2025).
cancer (continued). "In 2023, Nanjing Damei Biopharmaceutical developed ATR inhibitors particularly effective against cancers with impaired DNA repair mechanisms, including those with BRCA1/2 mutations, PTEN loss, or ATM deficiency." (PMID 40256842, 2025). "DNA-PK, ATR, and ATM inhibitors have displayed significant potential effects in preclinical studies as targeted therapies for cancer." (PMID 40256842, 2025). "Until recently, many studies have identified that inhibitors of components in the ATM/ATR/CHK1 pathway in cancers can down-regulate PD-L1 expression and promote the immune microenvironment." (PMID 40740769, 2025). "This review discusses the critical roles of Ataxia Telangiectasia Mutated Kinase (ATM), ATM and Rad3-related Kinase (ATR), and DNA-dependent protein kinase (DNA-PK) in the DNA damage response (DDR) and their implications in cancer." (PMID 40256842, 2025). "ATM inhibition sensitises cancer cells to DNA-damaging agents, PARP inhibitors, and immune checkpoint blockade by modulating DNA repair mechanisms and immune responses." (PMID 40256842, 2025). "Clinically, DNA damage repair (DDR) inhibitors, including ATR inhibitors, ATM inhibitors, and DNA-PK inhibitors, have been applied to treat cancers like advanced solid cancers." (PMID 41285712, 2025). "Research consistently highlights the role of upregulated ATM signalling in cancer resistance to therapies such as chemotherapy and radiation." (PMID 40256842, 2025). "In summary, ATM inhibitors represent a promising therapeutic approach by targeting the DNA damage response in cancer cells, thereby compromising their ability to repair DNA and enhancing susceptibility to cell death." (PMID 40256842, 2025). "While activation of these pathways can induce cell cycle arrest to allow for DNA damage repair, cancers often have other cell cycle or DDR alterations that allow for continued proliferation even in the presence of activated ATR/ATM (Maréchal and Zou, 2013)." (PMID 40514450, 2025). "Approximately 10% of patients with aggressive PC carry germline pathogenic variants in genes with established roles in cancer predisposition (BRCA2, ATM, CHEK2, NBN, BRCA1, PALB2, BRIP1, BARD1)." (PMID 41465280, 2025). "The most concordant cancer susceptibility genes represented in the combined data were BRCA1, BRCA2 and ATM, with 13, 11, and 6 pathogenic/likely pathogenic germline variants, respectively." (PMID 41465149, 2025).